CXCR4 (C-X-C motif chemokine receptor 4)
Diseases named in the same sentence as CXCR4 in open-access papers (continued):
Sharing a sentence is not in itself a finding about the gene and the disease.
tumor (continued). "Taken together, we demonstrated that CXCR4 plays a crucial role in tumor angiogenesis required for OSCC progression, whereas TAITN induced by CXCR4 antagonism could be an effective anti-angiogenic therapeutic strategy in OSCC treatment." (PMID 31336612, 2019). "CXCR4-positive vessels were significant in the tumor area more abundantly than those in nontumor areas." (PMID 31336612, 2019). "The importance of BMs is also suggested by in vitro studies, which underline that NEN cells exhibit osteotropism and that the mechanisms involved in the formation of BMs, including the EMT and the alteration of RANKL/OPG and CXCR4/CXCL12 pathway, are similar to those found in other tumor types." (PMID 31500357, 2019). "Rather than assisting NK-mediated immune surveillance against tumor formation and metastasis, some reports have indicated that CXCR3- and CXCR4-mediated attraction of NK cells may impede immune responses." (PMID 31647037, 2019). "This treatment combines the ability of NK cells to eliminate tumor cells without prior sensitization with anti-CXCR4 treatment to decrease the incidence of metastasis." (PMID 31428099, 2019). "These biomarkers include ADAM17, MMP2, MMP9, and MMP11, survivin and CK19, vimentin, CXCR4, ING5, and Stanniocalcin2; in all of these examples, these molecules are overexpressed in tumoral GC tissues." (PMID 31249523, 2019). "Notably, we found a unique pathophysiological structure defined as tumor angiogenic inhibition triggered necrosis (TAITN), which was induced by the CXCR4 antagonism." (PMID 31336612, 2019). "In a study looking at mouse models of breast, colon, and liver tumors, knockout of HIF-1α and HIF-2α decreased tumor growth, but only HIF-2α knockout lead to decreased expression of macrophage colony-stimulating factor receptor (M-CSFR) and CXCR4 on tumor-infiltrating macrophages." (PMID 30931508, 2019). "Although several studies have shown a strong connection between CXCL12/CXCR4 signalling towards MSCs migration and the tumour homing capacity, the knockdown of these receptors does not inhibit the homing potential of MSCs." (PMID 30060445, 2018). "The role of CXCR7 in tumor migration is still not conclusive and further studies on its role with CXCR4 are needed." (PMID 29977203, 2018). "Moreover, the hypoxia environment allows an increase of expression of chemokine (C-X-C motif) receptor 4 (CXCR4), one of the components responsible for the invasion and migration of tumor cells." (PMID 30304861, 2018). "In addition, CXCL12-dependent stimulation of CXCR4 on tumor cells has been shown to activate key downstream pathways including PI3K/AKT/mTOR and ERK1/2, which promote tumor cell survival proliferation, migration, and angiogenesis." (PMID 30257500, 2018). "Even if the tumor spread-promoting effect of Bevacizumab is under debate, nevertheless, these data bear witness to a close interaction between tumor hypoxia and SDF-1/CXCR4 signaling as introduced in more detail in the next chapter." (PMID 30622535, 2018). "In addition, high expression of CXCR4 in tumor cells correlated with lymph node metastasis and with high expression of CXCL12 in tumor-harboring lymph nodes." (PMID 30257500, 2018). "In the previous study, we determined that NT21MP exerted its anti-tumor role by selectively blocking CXCR4 signaling pathways and the expression level of SDF-1α is low in MDA-MB-231 cell, which is the only ligand of CXCR4." (PMID 30104400, 2018). "Antitumoral activity was shown for CXCR4 antagonist BL-8040 in tumor bearing mice, where it induced robust mobilization of CD4+ and CD8+ T lymphocytes and DC in numbers that were significantly higher compared to tumor free naïve counterparts." (PMID 30622535, 2018). "One way tumor cells home to and colonize bone is via the CXCL12/CXCR4 signaling axis." (PMID 29865211, 2018).
tumor (continued). "Lymph endothelial cells secrete chemokines including chemokine (C-X-C motif) ligand 12 (CXCL12) and chemokine (C-C motif) ligand 21 (CCL21) to recruit tumor cells that express chemokine (C-C motif) receptor 7 (CCR7) and chemokine (C-X-C motif) receptor 4 (CXCR4)." (PMID 29805773, 2018). "The next paragraph introduces the impact of SDF-1/CXCR4 signaling on the crosstalk of tumor cells with non-transformed stroma cells and its function for the cancer stem(-like) cell phenotype." (PMID 30622535, 2018). "CXCR4 and CXCL12 were expressed mainly in S100-positive tumor cells and not in tumor-associated macrophages." (PMID 29515781, 2018). "Since CXCR4 activation appears not to be limited to its physiological ligands, it is of great interest to identify the CXCR4 activators in the tumor to better stratify the use of “under investigation” CXCR4 inhibitors." (PMID 29721166, 2018). "Moreover, CXCR4 and CXCL12 tumor expression significantly contribute to serum CXCL12 concentrations." (PMID 30012106, 2018). "CXCR4 and CXCL12 play a pivotal role in tumor development and metastasis." (PMID 30105558, 2018). "It is also compelling that CXCL12 and CXCR4 were both expressed more highly in the tumours of patients without angioinvasion or lymphatic invasion and vice versa." (PMID 29887884, 2018). "Surprisingly, the anti-CXCL12 antibody failed to suppress tumor growth indicating that inhibition of the CXCL12/CXCR4 axis is not responsible for antitumor activity." (PMID 29682200, 2018). "Highly expressed CXCR4 contributes to the increased migration and invasion of HCC cell in the EMT system, and some studies suggest that CXCR4 accumulates at the perivascular region and tumor border." (PMID 29734668, 2018). "In addition to its function in tumor biology, SDF-1/CXCR4 signaling controls multiple physiological processes in hematopoiesis, T, B and NK cell development and the organization of the immune system." (PMID 30622535, 2018). "Superior immune responses as shown for CXCR4 antagonist BL-8040 is not solely owing to a selectively reduced recruitment of Treg cells into the tumor, and an increase in the number of immune and progenitor cells." (PMID 30622535, 2018). "Previous work demonstrated that radiation induces tumor invasiveness by increasing tumor-derived CXCL12 at the invasive tumor border, which may enhance the potential for CXCR4 signaling." (PMID 30451884, 2018). "For example, N1 neutrophils produce higher levels of TNFα, NO, and ROS, and are able to kill cancer cells whereas N2 neutrophils express high levels of C-X-C chemokine receptor type 4 (CXCR4 or CD184), gelatinase B/MMP9, among other markers, and act as mediators of tumor progression." (PMID 29719508, 2018). "With this assumption, it is conceivable that therapies strengthening the CXCR4/CXCL12 axis could potentiate extracellular matrix degradation favoring NK (and T) cells migration toward tumor cells." (PMID 30364222, 2018). "High expression of SOX11 in tumor cells could lead to a more aggressive disease course with increased proliferation and cell survival, by activating FAK and CXCR4." (PMID 29520657, 2018). "Despite the absence of significant activity with the F50067 CXCR4 inhibitor in this study, we believe that egression of tumor cells to the blood stream can still represent a novel therapeutic approach for MM." (PMID 29844860, 2018). "Additionally, the CXCR4/CXCL12 axis is a volatile system, part of a large network of the extracellular matrix/tumor cell microenvironment with high spatiotemporal differences." (PMID 30191351, 2018). "Regulation of CXCR4 by CXCR7 receptor has been reported by different, and sometimes opposite, mechanisms depending on the cell type; thus, the different tumor types could have a different regulation depending on their cell of origin." (PMID 29920526, 2018).
tumor (continued). "Similarly, TGF-β1, derived from breast cancer cells, increases the levels of miR-494 in MDSCs, enhances CXCR4-mediated MDSC chemotaxis, contributes to the accumulation of MDSCs in tumor tissues, and facilitates the invasion and metastasis of tumor cells." (PMID 30443251, 2018). "In recent years, the alarmin HMGB1, which can be massively released within the tumor microenvironment, has also been described to form a complex with the chemokine CXCL12 enhancing CXCR4-mediated signaling, thus providing an additional regulation of the activity of the chemokine system." (PMID 30319638, 2018). "In order to determine the mechanism by which fibrocytes were recruited into the tumor environment, we performed human-specific gene profiling using tumor tissues, and found that C–X–C motif chemokine ligand 12 (CXCL12), the ligand of CXCR4, played a role in the recruitment of fibrocytes." (PMID 29286323, 2017). "Moreover, PDX take rate correlated with patient OS and DFS, tumour stage, SUV, and presence of CD133+/CXCR4+/EpCAM− cells, consistent with more aggressive tumours prone to disseminate." (PMID 28751748, 2017). "We conclude that the effects of PT on the interaction of endothelial and tumor cells in vitro are based neither on an influence on cell adhesion molecules nor on the CXCL12/CXCR4 system." (PMID 29100413, 2017). "Moreover, treatment with CXCR4 antagonist T140 and analogues like Ac-TZ14011 inhibited tumor growth." (PMID 28549419, 2017). "Baseline H-score for CXCR4+ tumor was not prognostic of progression-free survival (PFS) or overall survival (OS)." (PMID 28299514, 2017). "It is important to note that our expression scoring did not consider CXCR4 staining on tumor vasculature, which was often CXCR4+ (below, and data not shown)." (PMID 29088715, 2017). "The volumes of the tumors were calculated every three days and showed no impact of CXCR4 on the tumor formation ability of ECSCs after transfection with sh-CXCR4 (p<0.001)." (PMID 28193907, 2017). "Chemokine receptor 4 (CXCR4) and its chemokine ligand 12 (CXCL12) have been identified with significantly elevated levels in various malignancies including GC, which correlates with the survival, proliferation, angiogenesis, and metastasis of tumor cells." (PMID 28544785, 2017). "After 1 hour, we found that the transduced MSCs, with and without CXCR4, reached the tumor site and remained, even after 24 hours." (PMID 28740515, 2017). "Neither baseline CTC counts or CXCR4 expression in tumor tissue or CTCs were predictive of treatment response for CXCR4 peptide antagonist LY2510924 plus CE versus CE alone." (PMID 28299514, 2017). "Recently, we reported that CXCR4 and CD133 expression identified a discrete population with stem cell properties in human ovarian cancer cells that might be critical for tumor development and chemo-resistance." (PMID 28566721, 2017). "CXCR4 and ETA were detected only in a few cases on the tumor cells." (PMID 29163802, 2017). "It was reported that HIF-2α deficient TAMs expressed lower levels of the chemokine receptor CXCR4 and failed to accelerate tumor growth." (PMID 28197019, 2017). "Besides, radiolabelled CXCR4 ligands, such as the Ga-68 labelled receptor ligand CPCR4-2, have been shown to be excellently suited for CXCR4-based PET diagnostics, especially in highly proliferative tumor entities." (PMID 29163802, 2017). "Finally, to test the possible therapeutic utility of pharmacologic inhibition of the Cxcl12/Cxcr4 axis on antral tumor development, we treated Mist1-CreERT; Cxcr4-EGFP; Apcflox/flox mice with AMD3100, a specific inhibitor of CXCR4." (PMID 29340033, 2017). "In our analysis, despite a weak positive correlation between CXCR4+ tumor and CXCR4+ CTCs, CXCR4 overexpression in tumor was not a prognostic factor for survival outcomes." (PMID 28299514, 2017).
tumor (continued). "The chemokine CXCL12 is constitutively secreted by bone marrow stroma cells in CLL and binds CXCR4 on the surface of CLL cells to direct chemotaxis, support tumor survival, and activate various signaling pathways, including STAT3 by phosphorylation of its serine 727 residue." (PMID 29379494, 2017). "CXCL12/CXCR4 is overexpressed by tumour cells, but not by murine stromal peritumoral cells which only produce CXCR4." (PMID 28386296, 2017). "In addition, the suppressive effect of SIS3 on cancer progression was also associated with inhibition of angiogenesis (CD31 and VEGF) and tumour-invasive and metastatic activities, including the expression of MMP-2, MMP-9, MMP-13 and CXCR4." (PMID 28262747, 2017). "As another limitation, SDF-1α/CXCR4 signaling is not the only pathway to promote tumor cell migration." (PMID 28978091, 2017). "Evaluation of immune cells in the CXCR4 positive tumors revealed the presence of minor amounts of immune cells in the tumor (1.0–1.3%), which did not influence the visualization of the tumor." (PMID 28549419, 2017). "CXCR4 baseline overexpression in tumor (≥210 H-score) was not prognostic of shorter PFS or OS in patients with ED-SCLC." (PMID 28299514, 2017). "Briefly, the staining intensity (weak, moderate, strong) and the number of labeled tumor cells were analyzed, with the CXCR4-negative tumor samples being scored as 0 or 1+, and CXCR4-positive tumor samples classified as 2+ or 3+." (PMID 29285291, 2017). "In summary, positive CXCR4 expression in tumor tissue was not significantly prognostic of survival in 89 patients with ED-SCLC in the present analysis." (PMID 28299514, 2017). "In addition, we demonstrate that the co-administration of the novel brain-penetrating CXCR4 antagonist, PRX177561, with bevacizumab or sunitinib inhibited tumor growth and reduced the inflammation." (PMID 28057017, 2017). "M-E5 could inhibit the migration of CXCR4-overexpressing MCF-7 and HepG2 tumor cells and enhance the sensitivity of tumor cells for Dox in vitro." (PMID 28793338, 2017). "Furthermore, the CXCL12/CXCR4/CXCR7 axis has been implemented in carcinogenesis and tumor progression." (PMID 28445977, 2017). "In ex vivo IHC up to 60% of tumor cells showed CXCR4 expression, however, in semiquantitative evaluation IRS was rather low (median IRS of 3) indicating only a limited number of CXCR4 receptors on the cell surface of tumor tissue." (PMID 29221153, 2017). "Interestingly, many of these genes are known to be involved in cell-cycle function (CDK2, CDK6, CCNB1, CEP55, CENPF), transcriptional regulation/tumor suppression (FOXO3, TOP2A), DNA-damage response (ASPM, XRCC4), and tumor progression (CYR61, MACC1, CXCR4)." (PMID 28482906, 2017). "Indeed, in only CD90+ CXCR4+ transplanted mice it was possible to detect tumor cells in circulation and tumor metastasis in distant organs thus suggesting that CD90+ CXCR4+ CTCs potentially retain stem-like metastasis initiating capability." (PMID 27738343, 2017). "Baseline tumor tissue CXCR4 expression was not prognostic of either PFS or OS in the overall study population." (PMID 28299514, 2017). "Moreover, forced expression of CXCR4 and COX2 resulted in a significant increase in tumor cell invasion." (PMID 27974694, 2017). "Moreover, when the CXCR4 blocking Ab was injected into the RL95-2 + EMSC group, a significant decrease was observed in tumor weights (1025 ± 45 mg, p < 0.05)." (PMID 29383153, 2017). "Our observation, that elevated baseline CXCR4 expression in CTCs (≥7% CXCR4+ CTCs) is prognostic of worse PFS in ED-SCLC, whereas CXCR4 overexpression in tumor is not, has several possible explanations beyond study design." (PMID 28299514, 2017). "HCC patients with CXCR4-positive tumor capillaries exhibited significantly higher serum AFP values (p = 0.035) as well as a distinctly higher Ki-67 index (p < 0.001) than those with CXCR4-negative tumor microvessels." (PMID 29282035, 2017).
tumor (continued). "Indeed, primarily in ER-positive invasive ductal cancer, we observed significant upregulation of COUP-TFI and CXCR4 and downregulation of CXCR7 and CXCL12, and the levels of these changes showed correlations with tumor grade." (PMID 28666461, 2017). "An increased grafting rate for tumours derived from patients with worse outcome (p = 0.006), higher stage (p = 0.038) and higher CD133+/CXCR4+/EpCAM− stem cell content (p = 0.019) was observed whereas a trend towards an association with SUVmax higher than 8 (p = 0.084) was detected." (PMID 28751748, 2017). "To evaluate expression of these phenotypes in cell based model, we analyzed the expression of the commonly used tumor markers phosphorylated NF-kB (p-NF-kB), phosphorylated STAT (p-STAT), CXCR4 and phosphorylated extracellular signal-regulated kinase (p-ERK) MAP kinase, by immunofluorescence." (PMID 29100333, 2017). "In particular, the use of nanoparticles simultaneously delivering CXCR4 antagonist ADM3100 and siRNA sequences targeting the VEGF gene, has allowed to synergistically control tumor angiogenesis and prevent local and distant tumor growth." (PMID 29240722, 2017). "Thus, although CXCR4 and ETA are hardly expressed by the tumor cells themselves, both receptors clearly enable an indirect targeting of the tumors via their blood vessels, thus depriving them of their supportive environment." (PMID 29163802, 2017). "In summary, our study showed that cell adhesion molecules and the CXCL12/CXCR4 chemokine system is not involved in the PT-induced interaction of tumor cells with the endothelium." (PMID 29100413, 2017). "To elucidate the functional role of the Cxcl12/Cxcr4 axis in antral tumorigenesis, we generated Tie2-Cre; Cxcl12flox/flox mice with targeted deletion of Cxcl12 in endothelial cells, and used these animals in the MNU tumor model." (PMID 29340033, 2017). "Our study did not differentiate between isoforms of CXCR4 detected in biopsied tumor and blood CTCs, the clinical relevance of which is not known." (PMID 28299514, 2017). "In comparison to CXCR4 inhibition as a monotherapy, standard chemotherapy composed of cisplatin and etoposide reduced the growth of the primary tumor by 71% (P<0.01) but completely failed to suppress metastasis formation." (PMID 27835905, 2016). "Hence, it is important to know the status of both CXCR4 up regulation and GNG4 down regulation for the inhibitors to act effectively in reducing tumor cell migration and infiltration." (PMID 27382437, 2016). "Further investigation into the potential negative impact of CXCR4 activation on tumor progression is warranted in preclinical studies of EZH2-inhibition." (PMID 27528222, 2016). "To examine the effect of CXCR4 knockdown on the invasion pattern of GL26-Cit tumors, we implanted 1000 GL26-Cit-Sh2CXCR4 cells or control GL26-Cit-NT cells into the striatum of NSG mice (N= 4/group) and examined the initial course of tumor progression." (PMID 27863376, 2016). "No significant changes in tumor weights were observed in mice harboring low-CXCR4 expressing MDA-MB-231 tumors." (PMID 26848769, 2016). "The CXCR4 and SDF-1 axis is important for tumor cell proliferation and survival." (PMID 26954567, 2016). "This work highlights the importance of BCR responsiveness towards CXCR4 downregulation, irrespective of the IGHV mutational status, on progression of tumor burden." (PMID 27127886, 2016). "Thus, it is possible that CAFs within breast tumors exert tumor-promoting effects largely through the secretion of SDF-1α, which acts through not only the cognate receptor CXCR4 on cancer cells but also the recruitment of MDSCs for immune escape." (PMID 27996037, 2016). "The same therapeutic regimen did not result in tumor growth reduction in low-CXCR4 MDA-MB-231 xenografts." (PMID 26848769, 2016).